APP (amyloid beta precursor protein)
Diseases named in the same sentence as APP in open-access papers (continued):
Sharing a sentence is not in itself a finding about the gene and the disease.
cognitive decline (continued). "Rare mutations in APP, PSEN1, and PSEN2 cause ADAD; however, the mechanisms by which altered APP processing leads to changes in tau and cognitive decline remain poorly understood." (PMID 30045758, 2018). "Cognitive decline (spatial learning, measured by the radial four‐arm maze assay) has been reported in APP/PS1 mice." (PMID 29472246, 2018). "Long term feeding with the same high fat diet used in the present study accelerated cognitive decline in APP/PSEN1 mice to a greater extent than wild-type littermates, and increased β-amyloid accumulation, tau phosphorylation and inflammatory response." (PMID 29618789, 2018). "The triplication of APP represents a strong evidence on the influence of HSA21 trisomy in the progression to AD-like cognitive decline in DS population." (PMID 30410750, 2018). "In this study, we addressed if chronic ES exposure accelerated or aggravated AD-related cognitive decline and alterations in the process of adult neurogenesis in APP/PS1 mice, a classic model for aspects of AD." (PMID 29563870, 2018). "In the current study, the effects of intracerebral MenSC transplantation on Aβ deposition, tau pathology and cognitive decline were evaluated in APP/PS1 double-transgenic mice for the first time." (PMID 29740283, 2018). "With the help of BDNF treatment, deposition of Aβ in the brain was restrained and the cognitive decline was postponed in APP/PS1transgenic mice." (PMID 29937713, 2018). "Exposure to 3-week long maternal separation thus led to a more severe Aβ phenotype as well as more severe cognitive decline in APP/PS1 mice, relative to 1-week of chronic ES exposure in our current study." (PMID 29563870, 2018). "Lactate amount in frontal cortex and interstitial fluid of the hippocampus was elevated in APP/PS1 transgenic mice having cognitive decline." (PMID 30563553, 2018). "This miRNA family targets BACE‐1 secretase, which cleaves amyloid precursor protein (APP) and generates toxic Aβ species, thereby contributing to synaptic loss and cognitive decline in AD." (PMID 29972883, 2018). "This is in accordance with the presumed compensatory mechanisms acting in young APP-KO mice preventing the onset of cognitive decline as observed in the elderly mice." (PMID 28163681, 2017). "Since BDNF counteracted the effects of the Aβ1−42 oligomers on neuronal apoptosis, we next sought to determine the roles of BDNF in the aggregation of Aβ and the cognitive decline of the APP/PS1 Tg mice." (PMID 28377712, 2017). "In our study, BDNF played pivotal roles in suppressing the deposition of Aβ and reducing cognitive decline of the APP/PS1 Tg mice." (PMID 28377712, 2017). "In fact, a polymorphism in APP that reduces APP processing by BACE1 protects humans from sporadic AD and normal aging-dependent cognitive decline." (PMID 25247712, 2014). "Transgenic mouse models overexpressing APP develop robust AD-like amyloid pathology in the brain and show various levels of cognitive decline." (PMID 23663320, 2013). "D-Ala2GIP improved memory in WT mice and rescued the cognitive decline of 12 months old APP/PS1 mice in two different memory tasks." (PMID 23601582, 2013). "Nevertheless, our findings clearly indicate that continuation of exercise is necessary to rescue HFD-induced aggravation of cognitive decline in APP transgenic mice." (PMID 24023774, 2013). "Others have shown that cognitive decline in transgenic mice, due to expression of familial disease mutant forms of APP, are ameliorated by deletion of tau." (PMID 23028730, 2012). "This suggests interaction between chronic cerebral hypoperfusion and APP overexpression for cognitive decline through altered Aβ metabolism." (PMID 21305033, 2011). "The resulting increase in APP protein levels results in increased Aβ levels, leading to synaptic dysfunction, neurodegeneration and, eventually, cognitive decline." (PMID 18684319, 2008).
cognitive decline (continued). "Another study using a fully automated home cage monitoring system demonstrated stability of cognitive ability in wild‐type mice over several months of testing, and a study of short‐term memory in an APP/PS1 mouse model of AD reported little cognitive decline between 1 month and 8 months of age." (PMID 41230607, 2026). "The levels of both proteins increased following treatment with 200μM H2O2, thus demonstrating their involvement in the context of cognitive decline, with an increase in APP and pTAU levels of approximately 28% and 19.1%, respectively, compared to control (p < 0.05)." (PMID 40807615, 2025). "Additionally, in the open field test, APP/PS1 mice spent significantly less time in the central area, a behavior associated with heightened anxiety and cognitive decline." (PMID 41184271, 2025). "Additionally, cholesterol dysregulation can disrupt APP processing and contribute to AD pathology and cognitive decline." (PMID 41451799, 2025). "To further characterize the molecular mechanisms underlying the effects of astrocytic Hevin overexpression in age‐mediated cognitive decline, we performed proteomic evaluation of the hippocampus from APP/PSEN and WT animals treated with AAV‐GFAP‐Hevin or AAV‐GFAP‐Mock for 6 months." (PMID 39935382, 2025). "In addition to its enzymatic role, AChE interacts with amyloid precursor protein (APP), promoting amyloid-beta (Aβ) aggregation, which accelerates neurodegeneration and worsens cognitive decline." (PMID 40726602, 2025). "Indeed, inducing vascular damage through chronic cerebral hypoperfusion (CCH) exacerbates cognitive decline in APP/PS1 mice." (PMID 41041058, 2025). "Likewise, while administration of AAV-YAPdeltaC protects against cognitive decline and pathological changes, including increased extracellular Aβ and ER instability, in 5xFAD and APP-KI mice, intracellular Aβ levels remain unchanged." (PMID 41013661, 2025). "Gal‐9 interacts with Aβ and accelerates its aggregation, generating Gal‐9‐Aβ fibrils, which induce neuroinflammation, synaptic dysfunction and cognitive decline, whereas the knockout of Gal‐9 rescues Aβ deposition, neuroinflammation and learning memory in APP/PS1 mice." (PMID 39485716, 2025). "The results showed that microinfarcts reduced amyloid deposits without affecting soluble amyloid levels in the brain of male and female APP/PS1 mice with 1-month survival, while causing rapid and long-lasting cognitive deficits in males and mild and transient cognitive decline in females." (PMID 40724648, 2025). "It is worth noting that cognitive decline in APP/PS1 mice usually starts at around 6 months old." (PMID 37307837, 2024). "Notably, the effect was reversible, as zinc supplementation protected APP/PS1 mice against cognitive decline by inhibiting NLRP3 inflammasome activation." (PMID 38648940, 2024). "5xFAD mice contain three AD familial mutations in humanized APP and two in PSEN1, and exhibit Aβ plaques, neurodegeneration, and cognitive decline as they age." (PMID 38915309, 2024). "Based on a report that male APP/PS1 mice demonstrate impaired glucose metabolism in the glucose tolerance test as early as 2 months of age, prior to amyloid beta deposition and cognitive decline at 8–9 months of age, we treated male APP/PS1 mice before the onset of this AD pathogenesis." (PMID 39519239, 2024). "Interestingly, conditional knockout (CKO) of SARM1 in the central nervous system (CNS, SARM1Nestin-CKO mice) delayed the cognitive decline in APP/PS1 AD model mice." (PMID 37307837, 2024). "Notably, Fe65-EXO-Cory-B induced autophagy in APP-expressing neuronal cells, leading to amelioration of the cognitive decline and pathogenesis in AD mice, demonstrating the potential of Fe65-EXO-Cory-B as an effective therapeutic intervention for AD." (PMID 37867176, 2023).
cognitive decline (continued). "In the present study, we investigated whether Lactobacillus paracasei-derived EVs can modify the expression of neurotrophic factors, and alleviate Aβ-induced pathology and cognitive decline in Tg-APP/PS1 mice." (PMID 37704750, 2023). "Cross-sectional MEG recordings were obtained of subjects carrying APP or PSEN1 mutations who had no signs of cognitive decline yet." (PMID 37608393, 2023). "Interestingly, ASA showed neuroprotective effects on restoring the levels of cell cycle-associated genes, which potentially contribute to the production and deposition of Aβ, leading to the cognitive decline of APP/PS1 Tg mice." (PMID 36263378, 2022). "Interestingly, MDP-treated mice performed the same as WT mice, suggesting that triggering of patrolling monocytes can delay the cognitive decline observed in the APP mouse at 6 months of age in females and males." (PMID 35883683, 2022). "IL-33 was confirmed to ameliorate AD pathology and cognitive decline in APP/PS1 mice." (PMID 36186141, 2022). "Inhibiting the loss of TREM2 may be one of the mechanisms by which running exercise improved glucose metabolism in the hippocampus and rescued cognitive decline in APP/PS1 mice." (PMID 35123512, 2022). "Many other studies have assessed the cognitive effects of H. erinaceus in other models of AD or cognitive decline/aging such as APP/swePS1dE9, SAMP8, ICR (Institute of Cancer Research) mice with injected amyloid peptides, and Sprague Dawley rats injected with d-galactose." (PMID 35877305, 2022). "Moreover, restricting BCAAs from diet delayed cognitive decline and lowered AD-related pathology in the cortex and hippocampus in APP/PS1 mice." (PMID 36359919, 2022). "This method could further be modified and applied to study the metabolism of non-APP BACE1 substrates, that have been implicated in chronic adverse events, such as cognitive decline, reported in Phase III BACE1 inhibitor clinical trials." (PMID 36056033, 2022). "From this, we found that ZD APP/PS1 mice had accelerated cognitive decline, but these deficits could largely be reversed by returning the mice to a diet that contained the recommended daily intake of zinc." (PMID 33597269, 2021). "Our study suggests that multifocal microinfarcts aggravate cognitive decline more potently in young APP/PS1 male mice compared to young females independently upon Aβ pathology via modulation of various mechanisms that include neurovascular coupling, neuroinflammation, and DKK1 expression." (PMID 35173711, 2021). "Likewise, the Barnes maze test revealed that MITOL deletion led to worsening cognitive decline in APP/PS1 mice." (PMID 33580194, 2021). "Therefore, indomethacin improved cognitive decline in APP/PS1 Tg mice by suppressing the production and deposition of Aβ and inducing Aβ efflux through a mechanism mediated by A2M-induced LRP1 activation." (PMID 34360951, 2021). "Furthermore, Mizuno and colleagues demonstrated that injections of IL-34 ameliorate cognitive decline and reduce Aβ burden in APP/PS1 mice." (PMID 33402196, 2021). "In the present study, to observe whether/how the miR-195 improves the cognitive decline in APP/PS1 mice, we first explored the optimal timing of intervention by evaluating the deposition of Aβ plague in the hippocampus and cortex." (PMID 33981225, 2021). "NOR shows a delayed cognitive decline in APP cKO 6 and 8 months old associated with a decreased volume of plaques in the hippocampus and cortex." (PMID 33402196, 2021). "The time of onset of cognitive decline in APP/PS1 mice varies." (PMID 32867800, 2020).
cognitive decline (continued). "Cognitive decline at age of 5 and 7 months in WT-BaP mice and APP/PS1-Vehicle might be partially due to synaptic defects and/or neurotransmitter imbalance but not loss/death of neurons." (PMID 32867800, 2020). "Furthermore, transplantation of APP−/− mESC-TEPs has a greater effect than that of APP+/+ mESC-TEPs in clearance of Aβ deposits in the CNS and reversal of cognitive decline." (PMID 32849642, 2020). "Two-month BaP exposure made cognitive decline more profound in both WT and APP/PS1 mice." (PMID 32867800, 2020). "Indeed, many studies have performed behavior tests and have shown cognitive decline in APP/PS1 mice when the mice were 8–12 month or even older." (PMID 32867800, 2020). "In addition to these mechanisms, CORT can induce a cognitive decline in APP/PS1 Tg mice by inducing apoptosis and decreasing the differentiation of neurons." (PMID 33519376, 2020). "All of these data suggest that FTS•B strongly ameliorated cognitive decline in APP/PS1 mice." (PMID 33059746, 2020). "Based on these studies, CORT treatment-induced cognitive decline in APP/PS1 Tg mice." (PMID 33519376, 2020). "Importantly, multiple studies have shown that early synaptic plasticity deficits or synapse loss, the disruption of neurotransmitters (e.g., serotonin and dopamine), and Aβ deposition in APP/PS1 mice correlate with cognitive decline." (PMID 32867800, 2020). "Finally, the phosphorylation of tau by Ca2+ contributed to the cognitive decline of APP/PS1 Tg mice." (PMID 31143112, 2019). "It is tempting to speculate that this process may contribute to the accelerated cognitive decline observed in APP/PSEN1 mice on this diet." (PMID 31101070, 2019). "We argue that insufficient sleep may disrupt excitatory signaling pathways mainly in the hippocampus of young APP/PS1 mice that further leads to early cognitive decline." (PMID 30872728, 2019). "Furthermore, administration of chemical chaperones that prevent ER stress ameliorates StARD1 upregulation and cognitive decline in APP/PS1/SREBP-2 mice." (PMID 31787922, 2019). "Our team previously found that a 4-month running exercise protocol could delay the cognitive decline of male APP/PS1 AD mice." (PMID 30174598, 2018). "More importantly, MenSCs protected APP/PS1 mice against cognitive decline and memory deficits." (PMID 29740283, 2018). "The onset of cognitive decline in APP/PS1 mice generally starts around 6 months of age." (PMID 29563870, 2018). "Considering that the level of Aβ has been implicate in the progression of cognitive decline in APP/PS1 mice, this might provide a possible explanation for the stronger impact of maternal separation stress on cognition decline." (PMID 29563870, 2018). "However, 1 study has shown that genetic knockdown of TLR2 accelerates the cognitive decline in APP-Tg mice." (PMID 29990310, 2018). "In addition, at the clinical dose of YXQN and donepezil, YXQN shows more significant effect than the cholinesterase inhibitor, donepezil, on improving the cognitive decline of APP/PS1 mice by 2 months administration." (PMID 28603494, 2017). "Similarly, patients with Down syndrome (trisomy 21) who carry three copies of the APP gene develop AD-like Aβ and tau neuropathology, leading to cognitive decline." (PMID 28197669, 2017). "The BDNF treatment improved the cognitive decline of the APP/PS1 Tg mice." (PMID 28377712, 2017). "Additionally, the BDNF treatment has the ability to alleviate the aggregation of Aβ and reduce the cognitive decline of the APP/PS1 Tg mice." (PMID 28377712, 2017). "Additionally, the BDNF treatment clearly decreased the deposition of Aβ and reduced the cognitive decline of the APP/PS1 Tg mice." (PMID 28377712, 2017). "Therefore, this study used 12-month-old male APP/PS1 mice to detect the effects of ICS II on cognitive decline and Aβ production." (PMID 28337142, 2017).
cognitive decline (continued). "Moreover, a peculiar CSF Aβ peptide signature was associated to cognitive decline in SCZ, suggesting a dysmetabolism of APP also in this psychiatric disorder." (PMID 26869919, 2016). "A key focus will be to emphasise that systemic inflammation and co-morbidity can significantly influence cognitive decline in animals without mutations in APP and Tau genes, thus focussing on research oriented towards late onset dementia." (PMID 25802557, 2015). "Further, it raises concerns about controls used in most mouse experiments; i.e. studies of age-related cognitive decline should use mice expressing wild-type APP at comparable levels to over-expressed mutant-APP, alongside the commonly used non-transgenic wild-types as controls, but usually do not." (PMID 25231068, 2014). "This outcome is supportive of recent data suggesting that APP processing derivatives or the overexpression of full length APP may contribute to cognitive decline in APP transgenic mouse models." (PMID 23663320, 2013). "However, D-Ala2GIP improved memory in WT mice and rescued the cognitive decline of 12 month-old APP/PS1 mice in two different memory tasks." (PMID 23601582, 2013). "It was shown that this peptide could be peripherally introduced into a transgenic APP mouse, where it effectively entered the brain and prevented/reversed oligomer formation, amyloid deposition, and cognitive decline." (PMID 22844635, 2012). "Indeed, a cognitive decline condition in vitro increased APP and pTAU levels." (PMID 40807615, 2025). "BACE1, implicated in AD pathogenesis, through APP cleavage and Aβ formation, was also associated with triglycerides, TG:HDL, and VAI, suggesting lipid levels may influence its activity and contribute to mechanisms of cognitive decline." (PMID 40665476, 2025). "Since the cognitive decline is based on an impairment of neuronal expression, pTAU and β-amyloid (APP) activities were investigated as major markers of cognitive decline, given that their alteration could induce hyperphosphorylation of pTAU and aggregation of APP." (PMID 38396866, 2024). "In addition, recent studies have reported a coding mutation (A673T) in the APP gene that protects against AD and cognitive decline in the elderly without AD, possibly by reducing the formation of amyloidogenic peptides." (PMID 37285261, 2023). "In Aβ-induced BV-2 cells and APP/PS1 mice, the NLRP3 inflammasome is activated and amounts of proinflammatory cytokines including IL-1β, IL-6, IL-18, and TNF-α are subsequently secreted, which are accompanied by the cognitive decline and memory loss of APP/PS1 mice." (PMID 35237381, 2022). "Transgenic overexpression models overexpress human APP and/or PSEN1 carrying familial AD-causal mutations; in these models relatively high expression of the transgene is driven by an artificial promoter, resulting in time-dependent Aβ deposition and coinciding cognitive decline." (PMID 35747206, 2022). "Furthermore, the authors showed that a pericyte deficit causes tau pathology and early neuronal death, resulting in cognitive decline in APP knockout transgenic mice, but not in APP overexpressing transgenic mice." (PMID 35453494, 2022). "Second, a mutation in human APP, which reduces cleavage by BACE1, leads to a reduction in cerebral Aβ of approximately 20%, with carriers showing lifelong protection against AD and cognitive decline (although issues with the mutation affecting aggregation of Aβ peptides cannot be fully excluded)." (PMID 35352880, 2022). "Additionally, we are currently crossing Rlip knockout mice with several APP and Tau transgenic mouse strains to evaluate whether reduced Rlip expression exacerbates cognitive decline in these strains." (PMID 34831336, 2021). "Indeed, a general overexpression of Prnp and App in 3- and 6-month-old APP/PSEN1-Tg mutant mice could also contribute to cognitive decline, since previous studies found alterations of these proteins in cortical areas and peripheral blood of MD." (PMID 33795014, 2021).